CGAS (cyclic GMP-AMP synthase)
Diseases named in the same sentence as CGAS in open-access papers (continued):
Sharing a sentence is not in itself a finding about the gene and the disease.
breast carcinoma (continued). "In parallel, we investigated the correlation between cGAS-STING inflammatory signaling and different molecular breast cancer subtypes, and its association with different genomic instability metrics using data from the TCGA and METABRIC cohorts." (PMID 38167507, 2024). "In summary, our study confirms that hyperactivated AKT1 in endocrine‐resistant breast cancer can interact with TBK1 to block the activation of cGAS‐STING signaling." (PMID 39023171, 2024). "Potent DNA-damaging agents, such as anthracyclines, as utilised in breast cancer, are capable of inducing the production of cytosolic DNA with subsequent activation of the cGAS-STING pathway in DNA repair-proficient models." (PMID 39395265, 2024). "In the panel of breast cancer cells, a significant increase in cytosolic dsDNA, cGAS and STING was observed across the cell lines, but they returned to baseline levels after expanding them." (PMID 38926422, 2024). "In summary, our combined results show that cGAS-STING inflammatory signaling is elevated in breast cancers with genomic instability." (PMID 38167507, 2024). "In this study, we showed that the cGAS-STING pathway was differentially activated in different breast cancer subtypes, with TNBCs showing the highest activation." (PMID 38167507, 2024). "Recent studies also reveal antimitotic therapies activating the cGAS/STING pathway directly in breast cancer cells, supporting better response to genotoxic treatments and immunotherapy." (PMID 38506114, 2024). "Our results show that the TBK1‐dependent activation of IRF3 is blunted in endocrine‐resistant breast cancer cells, thereby resulting in the suppression of cGAS‐STING signaling to mediate the endocrine resistance." (PMID 39023171, 2024). "Overall, our data indicate that endocrine‐resistant breast cancer cells are more insensitive to dsDNA‐induced activation of the cGAS‐STING pathway than parental cells." (PMID 39023171, 2024). "Breast cancer poses a significant threat to women’s lives; however, the activation of the cGAS-STING pathway, which triggers an immune response, offers promising prospects for its treatment." (PMID 37448962, 2023). "For example, repeated low radiation doses in a murine mammary carcinoma model create cytosolic DNA in tumor cells, activating the cGAS-STING pathway and the release of IFN-γ and subsequent T-cell activation." (PMID 37568788, 2023). "These contrasting findings suggest that the DDR-induced cGAS-STING signalling pathway plays a bidirectional regulatory role in breast cancer, highlighting the importance of investigating the mechanisms that control its directionality in this disease." (PMID 37448962, 2023). "ATM inhibition enhances the effectiveness of immune checkpoint blockade treatment in breast cancer by facilitating the cytoplasmic leakage of mtDNA and the activation of the cGAS-STING pathway." (PMID 37448962, 2023). "Germline defects in these genes can contribute to DDR dysfunction in breast cancer, thereby activating the cGAS/STING signalling pathway and eliciting an immune response." (PMID 37448962, 2023). "In the context of breast cancer, it has been shown that cGAS-STING signaling activation often yields paradoxical outcomes." (PMID 38203626, 2023). "For instance, c-di-AMP induces breast cancer cell apoptosis via the cGAS-STING pathway activation and regulation." (PMID 37448962, 2023). "Targeting the cGAS-STING-associated mitochondrial apoptotic pathway and mitochondrial ROS provides a novel avenue for breast cancer treatment." (PMID 37448962, 2023).
breast carcinoma (continued). "S-72 significantly inhibited cGAS-STING-IFNβ-IRDS signals in the paclitaxel-resistant breast cancer cells, removing the survival signals necessary for CIN cells and causing cell death." (PMID 37242532, 2023). "For example, repeated low radiation doses in a murine mammary carcinoma model create cytosolic DNA in tumor cells, activating the cGAS-STING pathway, release of IFN-γ and subsequent T-cell activation." (PMID 37568788, 2023). "In particular, it has already been suggested that EZH2 promotes the formation of CCFs in breast cancer cells and promotes breast cancer metastasis through the activation of the cGAS-STING pathway by CCFs." (PMID 37543653, 2023). "Particularly, the encouraging outcomes observed in using the cGAS-STING pathway for breast cancer treatment highlight its potential for further advancements." (PMID 37448962, 2023). "In particular, several studies showed that the Toll-like receptor 2 (TLR2) and the cyclic GMP–AMP synthase (cGAS)–stimulator of interferon genes (STING) pathways play a central role in breast cancer progression." (PMID 38203626, 2023). "In line with the observations seen in mouse breast cancer cell lines, a higher number of micronuclei and cGAS-positive micronuclei were observed in the cytosol of the invasive MDAMB231 compared to non-invasive MDAMB453 human cancer cells." (PMID 36882786, 2023). "Chemical inhibition of cGAS or TBK1 led to significantly reduced production of the IRF3 target CXCL10 in 66cl4 cells, indicating that the cGAS-STING-TBK1 pathway is important for IFN-I expression in the metastatic mouse breast cancer cells." (PMID 36882786, 2023). "It has been reported that exosomes containing tumor-derived DNA from irradiated breast cancer cells activate the cGAS-STING pathway in dendritic cells." (PMID 35563740, 2022). "It has also been reported that radiation induces IFN-beta in several types of cancer cells such as breast cancer cells, and the knockdown of cGAS or STING suppressed this effect." (PMID 35563740, 2022). "Here, we report that the enhancer of zeste homolog 2 (EZH2) can promote the formation of CCF and activate the cGAS–STING pathway to promote breast cancer metastasis." (PMID 35163710, 2022). "Mechanistically, in human breast cancer cell lines, it has also been shown that the cGAS/STING pathway is required for interferon activation induced by combined radiotherapy and anti-CTLA-4 immune checkpoint inhibition." (PMID 36387071, 2022). "Our research on the formation of CCF and the activation mechanism of cGAS has some new hints for the clinical treatment of breast cancer." (PMID 35163710, 2022). "Taken together, the results indicated that dual inhibition of H3K9me2 and H3K27me3 suppressed cGAS-STING signaling by decreasing CCF in breast cancer cells, thereby inhibiting SASP." (PMID 35409271, 2022). "In summary, we report that EZH2 promotes the formation of CCF in breast cancer cells and activates the cGAS–STING pathway to promote breast cancer metastasis." (PMID 35163710, 2022). "Upon deletion of cGAS using CRISPR-Cas9 or upon chemical inhibition of cGAS, several human and mouse breast cancer cell lines (BT594, 4T1) showed higher rates of apoptosis upon chromosomal mis-segregation." (PMID 36612027, 2022). "After the micronuclear membrane ruptures, USP7 in CCF can stabilize cGAS to activate the cGAS–STING pathway by reducing the ubiquitination of cGAS, thereby promoting breast cancer metastasis." (PMID 35163710, 2022). "TNBC is a relatively immunogenic form of breast cancer and one strategy to further increase immunogenicity is through activation of the cGAS-STING innate immune sensing pathway." (PMID 36497445, 2022). "Conversely, radiotherapy delivered at doses above 12-18 Gy induces Trex1 in other breast cancer models, which can hinder the pro-immune effects of radiotherapy by degrading cellular DNA upstream of the cGAS/STING pathway." (PMID 36387071, 2022).
breast carcinoma (continued). "Noteworthily, enhanced micronuclei formation in breast cancer cells exposed to G4 binders has been recently reported to trigger the activation of innate immune genes (i.e., type I interferon genes) via cGAS-STING." (PMID 35681604, 2022). "Our data show that EZH2 can promote CCF formation, and EZH2 activates the cGAS–STING pathway through CCF to promote breast cancer metastasis." (PMID 35163710, 2022). "Here we show that growth limitation by serum starvation activated the cGAS-STING pathway in breast cancer cells, and inhibition of cGAS-STING resulted in cell death through an autophagy-dependent mechanism." (PMID 35992877, 2022). "Further, Beclin-1, another autophagy mediator, was stained in breast cancer cells, but few cytoplasmic positive vesicles were detected and only occasional staining in cGAS positive MN." (PMID 34123836, 2021). "Chromosomal instability was shown to drive metastasis of breast cancer via activation of cGAS–STING signaling." (PMID 32382015, 2020). "KDM5B has been reported to suppress STING expression in breast cancer cell lines, thus short-circuiting the cGAS–STING–TBK1–IRF3 signaling axis important for innate immunity." (PMID 32117236, 2020). "In mouse models of breast cancer metastasis, evidence reveals that irradiated mesenchymal stromal cells exhibit activated cGAS-STING signaling, demonstrated by upregulated type I interferon-related genes and CCL5 expression, which promotes lung metastasis in a macrophage-dependent manner." (PMID 41573551, 2025). "Research has shown that JMJD8 is associated with cGAS-STING pathway and plays a role in various tumor microenvironments, but its relationship with breast cancer remains unclear." (PMID 40761260, 2025). "Using the poorly immunogenic murine breast cancer model 4T1,16 we investigated the immunogenicity of carbon ions with respect to the type-I-interferon response triggered by the cGAS/STING axis, which in turn is activated by the presence of dsDNA foci in the cytoplasm." (PMID 40486289, 2025). "Overview of the mechanisms andfunctions of cGAS-STING in breast cancer." (PMID 40567603, 2025). "The cGAS-STING pathway exerts a dual regulatory role in the breast cancer microenvironment: on one hand, it activates dendritic cells (DCs) and CD8+ T cells; on the other hand, its immunostimulatory effects can be counteracted by immunosuppressive cells such as Tregs and MDSCs." (PMID 41573551, 2025). "systematically analyzed the prognostic value of cGAS-STING related genes (CSRG) in breast cancer patients by obtaining 1,087 breast cancer samples and 179 normal breast tissue samples from The Cancer Genome Atlas (TCGA) and Genotype Tissue Expression (GTEX) databases, identifying 35 CSRGs." (PMID 40567603, 2025). "Breast cancer subtypes exhibit divergent regulation of the cGAS-STING pathway." (PMID 41573551, 2025). "In breast cancer, the activation of the cGAS-STING pathway plays a complicated role." (PMID 40861477, 2025). "Another recent study showed that a nuclear receptor, NR1D1, enhances the antitumor CD8 + T cell response to breast cancer by promoting DNA damage-induced accumulation of cytosolic DNA fragments, which leads to activation of cGAS-STING signaling and downstream type I IFN signaling." (PMID 41299712, 2025). "This review systematically summarizes the pivotal roles of the cGAS-STING signaling pathway in breast cancer initiation, progression, drug resistance, and therapeutic responses, as well as its profound impact on tumor advancement and microenvironmental remodeling." (PMID 40567603, 2025). "We further confirmed whether targeting AKT1 could reverse the activity of the cGAS‐STING pathway in endocrine‐resistant breast cancer cells." (PMID 39023171, 2024). "To address whether cGAS-STING signaling was related to levels of genomic instability in breast cancer samples, we immunohistochemically analyzed replication stress markers γH2AX and phospho-RPA32 (Ser33) in our breast cancer cohort." (PMID 38167507, 2024).
breast carcinoma (continued). "Moreover, data from the I-SPY2 clinical trial (n = 71) confirms that higher cGAS-STING scores are observed in breast cancer patients who responded to immunotherapy combined with chemotherapy." (PMID 38167507, 2024). "Finally, data from the I-SPY2 immunotherapy cohort was used to assess the involvement of cGAS-STING inflammatory signaling as a predictive factor for the response of breast cancer patients to immunotherapy." (PMID 38167507, 2024). "Based on these observations, we postulated that the cellular response to MYC-induced DNA damage may promote cGAS activation and tumour suppression in this transgenic breast cancer model." (PMID 38200309, 2024). "Mammary tumours from this genetic model induced by lentivirus-expressing Cre and control sgRNA (sgControl, which targets an intronic sequence on chromosome 2) exhibited abundant cytoplasmic DNA damage (gH2A.X) foci and cytoplasmic cGAS localization." (PMID 38200309, 2024). "However, the understanding of the relationship between ROS and the cGAS-STING pathway in breast cancer is limited, and further investigation is necessary to uncover new treatment options." (PMID 37448962, 2023). "Similarly, another study highlights that genotoxic stress induced by chemotherapy sustains DNA damage response and breast cancer cell resistance by triggering chronic cGAS-STING-dependent IFN production." (PMID 38203626, 2023). "In addition, the cGAS expression level was shown to correlate with Taxol sensitivity in a panel of breast cancer cell lines, and promoted the response to Taxol in a mouse xenograft model of cervical cancer." (PMID 37627155, 2023). "However, activation of the STING pathway also enhances the IL-6-dependent survival of chromosomally unstable breast cancer cells, suggesting a pro-tumorigenic effect of cGAS-STING signaling." (PMID 37816954, 2023). "However, when the cGAS-STING pathway is activated within the breast cancer TME, T helper/IL-17-producing CD8+ T -generated CAR-T cells show increased persistence in the TME and enhanced tumour control." (PMID 37448962, 2023). "However, cGAS-STING-related genes (CSRGs) have rarely been investigated for their prognostic value in breast cancer patients." (PMID 37051596, 2023). "Notably, a subset of IFN-regulated genes that constitute an IFN-related DNA damage signature (IRDS), which includes STAT1, provides protection against DNA damage sensed by cGAS-STING in breast cancer cell lines." (PMID 37349798, 2023). "The cGAS-STING-related genes risk score was also relevant to a series of clinic prognostic indicators such as tumor staging, molecular subtype, tumor recurrence, and drug therapeutic sensibility in breast cancer patients." (PMID 37051596, 2023). "Furthermore, depletion of extracellular cGAMP abrogated this immune cell infiltration in breast cancer models, suggesting that these radiation-induced immune effects are dependent upon the presence of extracellular cGAMP and the cGAS/STING pathway." (PMID 36387071, 2022). "Our research on the mechanism of CCF formation and cGAS activation has new implications for breast cancer treatment, suggesting that people may achieve the curative effect of breast cancer metastasis by targeting CCF with epi-modifying enzyme inhibitors." (PMID 35163710, 2022). "Moreover, cGAS-positive micronuclei were also observed after in vivo paclitaxel treatment of human breast cancer patient-derived xenografts (PDX) grown in immunodeficient mice." (PMID 31937780, 2020). "Importantly, either STING or cGAS KO or LMNB2 overexpression in donor breast cancer cells strongly decreased induction of paracrine propapoptotic effect by paclitaxel." (PMID 31937780, 2020).
breast carcinoma (continued). "More importantly, we present a combination strategy of STING agonists and AKT1 inhibitors that could block the positive feedback loop to maximize the activation of cGAS‐STING signaling in endocrine‐resistant breast cancer cells, overcoming endocrine resistance." (PMID 39023171, 2024). "In addition, MCA205 and 4T1 (breast cancer cell line) treated with palbociclib could also trigger cGAS-STING and downstream type I interferon pathway activation." (PMID 37833461, 2023). "Therefore, the cGAS-STING pathway may provide new approaches to enhance immunotherapy in breast cancer." (PMID 37051596, 2023). "However, the mechanisms by which CCF are formed in tumor cells and CCF activation cGAS promotes breast cancer metastasis remain unclear." (PMID 35163710, 2022). "Moreover, knock down of BRCA2 in human breast cancer cells activates the cGAS/STING pathway." (PMID 36387071, 2022). "The results revealed that cGAS and STING expression was low or undetectable in most breast cancer and murine tumor cell lines." (PMID 40830678, 2026). "The Human Protein Atlas (HPA) data showed low cGAS and STING expression in most breast cancer cell lines, with BT549 and MDA-MB-436 serving as approximate upper expression thresholds." (PMID 40830678, 2026). "The cGAS-STING signaling pathway exhibits distinct regulatory patterns and therapeutic implications across breast cancer subtypes." (PMID 41573551, 2025). "The cGAS-STING signaling pathway serves as a crucial bridge between innate and adaptive immunity, playing a dual role in breast cancer pathogenesis and treatment." (PMID 41573551, 2025). "Our study highlights the critical role of the cGAS-STING pathway, molecular subtypes, and the miR-26a-5p/HOXC13 axis in breast cancer immune modulation and therapy response." (PMID 40861477, 2025). "For example, PRMT1 overexpression is associated with increased arginine methylation and aberrant exon inclusion of SRSF1, which is essential for breast cancer cell growth; PRMT1 suppresses the anti-tumor immune response via arginine methylation of cGAS." (PMID 40744915, 2025). "The cGAS-STING pathway’s role and regulatory mechanisms in Luminal breast cancer are a hot research topic." (PMID 40567603, 2025). "Innovative nanomotors with an asymmetric structure show the ability to simultaneously activate the cGAS-STING pathway and block the PD-1/PD-L1 checkpoint, representing a promising strategy for breast cancer immunotherapy." (PMID 41007722, 2025). "Building upon extensively researched genes within the cGAS-STING pathway, we identified eight genes that serve as indicators of breast cancer’s responsiveness to anti-PD1 therapy." (PMID 40861477, 2025). "In HER2-positive breast cancer, STING agonists (e.g., ADU-S100) activate the cGAS-STING pathway to promote IFN-I secretion, enhancing APC maturation and cross-presentation." (PMID 40567603, 2025). "Activation of the cGAS-STING pathway also reportedly correlates with genomic instability and better responses to immunotherapy in breast cancer patients." (PMID 41299712, 2025). "Radiotherapy: Induces micronuclei-derived cytosolic DNA, activating cGAS-STING-dependent abscopal effects; clinically enhances systemic responses in oligometastatic breast cancer." (PMID 41573551, 2025). "This study evaluated the expression of cGAS, STING, and NF-κB-p65 by nanoparticles in human breast cancer MDA-MB-231 cells." (PMID 41050083, 2025). "Recently, there has been a growing interest in the activation of the cGAS-STING pathway through nanomaterials, providing new strategies for immunotherapy in breast cancer." (PMID 40567603, 2025). "By finely tuning cGAS-STING activity, we can enhance breast cancer immunogenicity and the efficacy of immune checkpoint inhibitors, offering more effective strategies for patients." (PMID 40567603, 2025).